PRL (prolactin)
Diseases named in the same sentence as PRL in open-access papers (continued):
Sharing a sentence is not in itself a finding about the gene and the disease.
breast cancer (continued). "Here, we show that the PRL-humanized Nod-scid-IL2Rγ (NSG) (NSG-Pro) mouse, a unique host with physiological levels of circulating hPRL in the absence of mPRL, supports the engraftment, growth, metastasis, and therapeutic responses of all common breast cancer subtypes." (PMID 34524841, 2021). "This latter role is supported by the association between prolactin/PRLR down-regulation and significantly better survival outcome in patients with breast cancer, which is consistent with the lack of anti-tumorigenic effects and therapeutic benefits observed in clinical trials with PRLR antagonists." (PMID 33335078, 2020). "Moreover, PRL via PRLR is able to promote migration and invasion of breast cancer cells." (PMID 33584543, 2020). "Time-dependent Cox proportional hazards models were used to calculate adjusted hazard ratios (HRs) and 95% confidence intervals (CIs) of breast cancer-specific mortality comparing use of antipsychotics with non-use, overall, and by prolactin elevating activitiy." (PMID 32831062, 2020). "Our results lead us to propose that the PR isoform-specific regulation of distinct regulatory responses in the cross-talk between prolactin and FASN might be involved in the diverse phenotypic outcomes arising from the prolactin/PRLR signaling axis in luminal breast cancer." (PMID 33335078, 2020). "Interestingly, a negative cross-talk between TGFβ and PRL pathways has been observed in mammary epithelial and breast cancer cells." (PMID 30987013, 2019). "Whereas ERα + breast cancer cells cultured in low density/compliant three-dimensional collagen I matrices respond to PRL predominantly by activating physiological JAK2/STAT5 signals, high density/stiff matrices shift PRL responses to pathological ERK1/2 signals and increase invasiveness." (PMID 28103936, 2017). "In the present study, we show that the incidence of mammary tumors induced by DMBA in OFA rats is not influenced by serum PRL and that the progression and regression of the tumors are dependent on the extent of differentiation produced in the mammary gland by the effects of parity and lactation." (PMID 25136563, 2014). "Also, clinical studies report that reducing circulating PRL levels did not improve the condition of advanced breast cancer patients." (PMID 24148306, 2013). "The present study analyzed 187 post-menopausal breast cancer patients to determine whether or not the serum hormonal levels of FSH, LH, P and PRL were associated with the expression of two key molecular markers, Ki67 and Her-2." (PMID 24137476, 2013). "Furthermore, 70-95% of human breast cancers express PRL receptor (PRLR), and many breast cancer cell lines express high levels of PRLR with evidence of proliferative or survival responses to PRL in vitro." (PMID 23758962, 2013). "Our results do not support the serotonin-mediated pathway for the prolactin-breast cancer hypothesis." (PMID 23227451, 2012). "How parity and prolactin interact with hormones important for breast epithelial proliferation is not yet clear, but may be important in breast cancer development." (PMID 23095343, 2012). "Our findings do not support a serotonin-mediated pathway for the prolactin-breast cancer hypothesis even after taking into account the extent of serotonin reuptake inhibition of individual SSRIs and the duration of their use." (PMID 23227451, 2012). "The role of PRL in tumorigenesis of canine breast cancer is not known to date." (PMID 22647582, 2012). "Furthermore, PRL partially rescued the knock-down of CPT1 enzyme activity induced by siRNA-mediated targeting of CPT1A in breast cancer cells, but not in normal breast epithelial cells." (PMID 21294903, 2011). "Lower breast cancer incidence rates, as reflected in marginally lower percentage mammographic density, in Afro-Caribbean women were not explained by levels of sex hormones, IGFs or prolactin as measured at a single time point postmenopausally." (PMID 19545414, 2009).
breast cancer (continued). "Both prolactin and its downstream protein effector, HSP90α, promote survival, as shown by apoptosis assays and by the addition of the HSP90 inhibitor, 17-allylamino-17-demethoxygeldanamycin (17-AAG), in both untransformed HC11 mammary epithelial cells and SKBR3 breast cancer cells." (PMID 19014541, 2008). "Prolactin levels did not vary by race/ethnicity, before or after adjusting for potential confounders: parity, age at first pregnancy, body mass index, family history of breast cancer, and menopause age and type (p-heterogeneity = 0.447) (data not shown)." (PMID 18053149, 2007). "Thus, it has been judged that it does not exert any influence on prolactin production by the pituitary, and that pituitary prolactin production is not involved in the development of breast cancer." (PMID 17543123, 2007). "mRNA for prolactin and its receptor has been found in normal breast tissues and in primary human breast cancers; while both receptor mRNA and protein are expressed in nearly all human breast cancers, they are not generally overexpressed." (PMID 15213724, 2004). "However, 11 out of 25 patients were treated with tamoxifen, and it has been shown recently that chronic tamoxifen treatment does not alter PRL plasma levels in postmenopausal women with breast cancer." (PMID 12698200, 2003). "Notably, our study provides evidence that inducing and/or maintaining PRL/PRLR signaling is critical in restricting and suppressing breast tumorigenesis and promoting its differentiation function may hold therapeutic value in breast cancer." (PMID 40157909, 2025). "Interestingly, our study showed that the previously controversial increase in prolactin levels with SSRI drugs was not significant in our analysis, and the SSRI-prolactin-breast cancer hypothesis does not hold up in the light of our findings." (PMID 37540479, 2024). "While this fact could have contributed to the increased odds of breast cancer found in this study with the use of any antipsychotic, this would also have been true for women using prolactin-sparing antipsychotics, where the odds of breast cancer was not increased." (PMID 38687213, 2024). "However, there are no clinical data on whether the reduction of PRL level affects the patients with endocrine resistance in breast cancer." (PMID 34651424, 2021). "In ER-positive/PR-negative luminal B-like breast cancer cells, however, FASN signaling might be co-opted as a negative regulator of the epithelial cell phenotype and, accordingly, its blockade might promote the restoration and activation of prolactin/PRLR-driven differentiation programs." (PMID 33335078, 2020). "Similarly, prolactin blockade in epithelial-like breast cancer cells has been shown to induce mesenchymal-like phenotypic changes and enhance invasiveness, whereas activation of PRLR in mesenchymal-like breast cancer cells suppresses mesenchymal properties and reduces invasive behaviors." (PMID 33335078, 2020). "As part of the Breast cancer and Exercise Trial in Alberta (BETA) we investigated: 1) the effects of increased levels of moderate to vigorous physical activity (MVPA) on levels of prolactin and 2) whether a higher level of activity led to larger changes in prolactin levels." (PMID 28717404, 2017). "Incorporation of therapeutic agents that inhibit the function of the hormone PRL or the PRLR receptor with those targeting the various signal transduction pathways, including those resulting from activation of HER2 could improve effectiveness in reversing resistance in breast cancer." (PMID 25193864, 2014). "Our data did not support the hypothesis that serum prolactin levels differ for women with PRL and PRLR genotypes associated with breast cancer; prolactin levels did not vary by genotype for any of the breast cancer-associated SNPs in this study (rs13436213, rs249537, and rs7718468)." (PMID 21470416, 2011).
breast cancer (continued). "Altogether, based on our bioinformatics analysis and functional validation experiments these results established a link between PRL/PRLR and Hippo pathway and as an important negative regulator of YAP-CCN2 pathway in breast cancer." (PMID 40157909, 2025). "Osteoclasts do not express the PRLR, so any effect of PRL on osteoclasts would be indirect, including via PRLR+ osteoblasts or PRLR+ breast cancer cells." (PMID 27782069, 2016). "Treatment with PRL further increased the expression of CPT1A at both the mRNA and protein levels in breast cancer cells, with no changes observed in normal breast epithelial cells." (PMID 21294903, 2011). "PRL stimulation increased the expression of CPT1A (liver isoform) at the mRNA and protein levels in both breast cancer cell lines, but not in 184B5 cells." (PMID 21294903, 2011). "Although PRL/PRLR inhibitors have not shown robust promise as monotherapies, there has been long term interest in their interaction with other treatment modalities, especially with anti-estrogens in ER+ breast cancers." (PMID 35784527, 2022). "Our finding that SFKs are key mediators of PRL-enhanced estrogen-induced growth in stiff, but not in compliant matrices begins to reconcile the apparent conflict between evidence for PRL activity and activated STAT5 in outcomes of ERα+ breast cancer." (PMID 25607819, 2015). "Accordingly, the restoration/activation of prolactin/PRLR signaling has been shown to promote cell differentiation and reverse highly proliferative, invasive, mesenchymal and tumorigenic phenotypes, such as those of the ER/PR double-negative MDA-MB-231 breast cancer model." (PMID 33335078, 2020).
pituitary adenomas (321 papers, 2006 to 2026). "Approximately 70% of pituitary adenomas are associated with syndromes characterized by excessive hormone secretion, with the most common types producing prolactin, growth hormone, and ACTH." (PMID 41393741, 2025). "It was found that a prolactin-secreting pituitary adenoma was associated with TMA (confirmed as von Willebrand factor-positive microthrombi in the arterioles and capillaries of several organs, primarily the heart and brain)." (PMID 40217615, 2025). "On the other hand, amongst the pathological causes, the most frequent etiology of hyperPRL is a PRL-secreting pituitary adenoma, the “prolactinoma”, which represents about the 40% of functioning pituitary adenomas." (PMID 38194218, 2024). "Hyperprolactinaemia occurring because of prolactin-secreting pituitary adenoma and associated adverse effects are significant problem, decreasing quality of life and demographics in general." (PMID 38311996, 2024). "X-linked acrogigantism (X-LAG) is a rare form of pituitary gigantism that is associated with growth hormone (GH) and prolactin-secreting pituitary adenomas/pituitary neuroendocrine tumors (PitNETs) that develop in infancy." (PMID 38481440, 2024). "The case with the highest mNTR had no visual loss, but was diagnosed due to systemic symptoms that were caused by a prolactin secreting pituitary adenoma." (PMID 37385651, 2024). "The most common causes of Hyper-PRL are pregnancy, pituitary adenoma, intracranial tumors, prolactin stimulants, and pharmacological conditions such as the administration of estrogen or heavy metals." (PMID 35098010, 2021). "Clinically, the leading cause of GH excess is a GH-producing pituitary adenoma (incidence/prevalence: 0.4–1.1 cases per 100,000/4–13 cases per 100,000), which occurs much more rarely than prolactin-secreting pituitary adenomas." (PMID 34948002, 2021). "Given the possibility of causing a pituitary adenoma, a dedicated MRI or CT of the pituitary should also be considered in patients with moderately increased prolactin levels for long-term." (PMID 34441908, 2021). "The typical symptoms of PRL-secreting pituitary adenomas are associated with the reproductive system, decreased libido, and menstrual changes in women." (PMID 34057414, 2021). "The patient refused neurosurgery; therefore, ANA 1 mg/day was added, achieving the normalization of the PRL levels and a reduction of the pituitary adenoma within the first 6 months of association therapy." (PMID 34173929, 2021). "According to literature, pituitary adenomas secondary to primary hypothyroidism are usually associated with elevated PRL levels." (PMID 32080117, 2020). "It has been demonstrated that the expression of Lgals3 (galectins) in pituitary adenomas is positively associated with the prolactin level in pituitary tumorigenesis." (PMID 32183190, 2020). "Associated with the appearance of pituitary adenomas, serum prolactin levels rose as transgenic mice aged." (PMID 30410667, 2018). "Prolactin variants changed in different subtypes of pituitary adenomas relative to control pituitaries." (PMID 30210449, 2018). "The most well-known association found in pituitary adenomas assessment, between GH and PRL, was present in 10.36% of the cases from group 1 and in 13.63% of the cases from group 2." (PMID 26078755, 2015). "About 50% of pituitary adenomas are prolactinomas that secrete prolactin and cause galactorrhea and hypogonadism." (PMID 25136513, 2014). "The implantation of GH-secreting cells from GH3 pituitary adenoma increases thymic size in aged rats, and GH administration increases thymic cellularity and thymic T cell proliferation in GH- and prolactin (PRL)-deficient dwarf DW/J mice." (PMID 19479077, 2009). "Pituitary adenomas that secrete excessive Prolactin may be associated with obesity, and some patients with prolactinomas or obesity have been reported to experience weight loss when serum Prolactin levels are normalized." (PMID 40659555, 2025).
pituitary adenomas (continued). "Elevated prolactin concentrations may be caused by prolactin-secreting pituitary adenomas, loss of dopamine inhibition by antipsychotic drugs, or systemic disorders." (PMID 39422626, 2024). "This is also observed that some of the neoplastic cells can secrete two hormones, including GH and prolactin, that serve to develop chimeric molecules for the treatment of pituitary adenomas associated with over-secretion of GH and PRL (discussed in detailed later)." (PMID 38203605, 2023). "In both genders, PRL excess, specifically when associated with pituitary adenomas, has been associated with a higher risk of MetS, adipose tissue dysfunction index and reduced glucose tolerance, with the normalization of PRL leading to an improved metabolic pattern." (PMID 37204690, 2023). "The metoclopramide test has been developed in the 70’s as a strong stimulator of PRL secretion and is used to distinguish hPRL due to pituitary adenoma from other causes of hPRL, with a cut off of 300% being admitted as a limit of PRL stimulation beyond which hPRL is unlikely due to PRLoma." (PMID 35250884, 2022). "Hook effect is a very rare occurrence nowadays with modern assays and might be considered in all cases of large (≥3 cm) pituitary adenomas associated with normal or mildly elevated PRL levels (≤250 ng/mL)." (PMID 35000899, 2022). "Chronic isotretinoin, anabolic androgenic steroids, and prolactin-secreting pituitary adenoma or, in this last case, its inhibitory treatment, can cause lacrimal gland atrophy, sicca syndrome, and dry eye syndrome, and a differential diagnosis of Sjögren's syndrome." (PMID 33470346, 2021). "Further studies on doses, time, and other susceptibilities to the long-lasting adverse effects of retinoic acid, anabolic androgenic steroids, and the repercussions of prolactin-secreting pituitary adenoma are necessary to confirm and expand upon these associations." (PMID 33470346, 2021). "The higher mortality observed could be related to the underlying disease, transsphenoidal surgery for pituitary adenomas, prolactin’s many diverse functions or unmeasured confounders." (PMID 34963443, 2021). "Other studies have reported that the cause of Hyper-PRL is mostly due to pituitary adenomas." (PMID 35098010, 2021). "The potential role of GPR101 in somatotropes initially came to light with the description of X-LAG, in which a duplication on chromosome Xq26.3 including GPR101 is associated with infant-onset GH and PRL-secreting pituitary adenomas that express high levels of GPR1017–9,37." (PMID 32958754, 2020). "Moreover, the pattern of those six PRL variants was significantly different among five subtypes of pituitary adenomas relative to control pituitaries." (PMID 30210449, 2018). "Other causes of female infertility were in the frequency of 12.3% endometriosis, 2.9% hyperprolactenemia i.e., an excessive amount of prolactin in the blood, usually caused by a pituitary adenoma but sometimes caused by endocrine side effects related to certain antipsychotic medications." (PMID 26150870, 2015). "Moreover, the overall proportional ratio of six PRL variants was significantly different among the five subtypes of pituitary adenomas (NF−, FSH+-, LH+-, FSH+/LH+-, and PRL+-adenomas) analyzed here with the Chi-square test performed with SPSS 22 software (p < 0.05)." (PMID 30210449, 2018). "Predictive factors of resistance to fgSRL (used in monotherapy) in GH&PRL co-secreting pituitary adenomas." (PMID 40590355, 2025). "The latest consensus on the diagnosis and management of prolactin-secreting pituitary adenomas recommends that pituitary surgery along with dopamine agonist therapy should be considered as a first-line treatment option in patients with microprolactinoma." (PMID 40199840, 2025). "Dopamine agonists (DAs) are the first-line therapy for prolactin-secreting pituitary adenomas as they are effective in improving symptoms and reducing tumor burden." (PMID 41156214, 2025).